SLAMF6 (SLAM family member 6)
Description:
Self-ligand receptor of the signaling lymphocytic activation molecule (SLAM) family. SLAM receptors triggered by homo- or heterotypic cell-cell interactions are modulating the activation and differentiation of a wide variety of immune cells and thus are involved in the regulation and interconnection of both innate and adaptive immune response. Activities are controlled by presence or absence of small cytoplasmic adapter proteins, SH2D1A/SAP and/or SH2D1B/EAT-2. Triggers cytolytic activity only in natural killer cells (NK) expressing high surface densities of natural cytotoxicity receptors. Positive signaling in NK cells implicates phosphorylation of VAV1. NK cell activation seems to depend on SH2D1B and not on SH2D1A. In conjunction with SLAMF1 controls the transition between positive selection and the subsequent expansion and differentiation of the thymocytic natural killer T (NKT) cell lineage (By similarity). Promotes T-cell differentiation into a helper T-cell Th17 phenotype leading to increased IL-17 secretion; the costimulatory activity requires SH2D1A. Promotes recruitment of RORC to the IL-17 promoter. In conjunction with SLAMF1 and CD84/SLAMF5 may be a negative regulator of the humoral immune response. In the absence of SH2D1A/SAP can transmit negative signals to CD4(+) T-cells and NKT cells. Negatively regulates germinal center formation by inhibiting T-cell:B-cell adhesion; the function probably implicates increased association with PTPN6/SHP-1 via ITSMs in absence of SH2D1A/SAP. However, reported to be involved in maintaining B-cell tolerance in germinal centers and in preventing autoimmunity (By similarity).
Synonyms: NTB-A; CD352; KALI; NTBA; KALIb; Ly108; SF2000
Tractability: Small molecule: it has a binding pocket of medium quality. Antibody: UniProt places it where antibodies can reach, with high confidence; its Gene Ontology location is reachable by antibodies, with high confidence; UniProt predicts a signal peptide or a membrane-spanning region; the Human Protein Atlas places it where antibodies can reach. PROTAC: ubiquitination databases record sites on it; its protein half-life has been measured.
Gene: Protein-coding gene on chromosome 1 (160,485,030 to 160,523,273, reverse strand). Ensembl gene ENSG00000162739.
Subcellular location: Cell membrane
Subcellular location (Human Protein Atlas): Cytosol; Plasma membrane
Pathways (Reactome):
Immune System: Immunoregulatory interactions between a Lymphoid and a non-Lymphoid cell
Gene Ontology:
Molecular function: identical protein binding; protein binding
Biological process: positive regulation of interleukin-17 production; positive regulation of natural killer cell mediated cytotoxicity; positive regulation of type II interferon production; T-helper 17 cell lineage commitment; immune response; T cell activation
Cellular component: extracellular exosome; plasma membrane; external side of plasma membrane; membrane
Genetic constraint (gnomAD): Loss-of-function variants: 21 observed, 39.94 expected, observed/expected ratio (o/e) 0.53, 90% interval 0.37 to 0.76. The upper end of that interval is the gene's LOEUF score, 0.76, which puts it in group 3 of 6, group 1 being the genes least tolerant of losing a copy. Missense variants: 341 observed, 405.25 expected, observed/expected ratio (o/e) 0.84, 90% interval 0.77 to 0.92. Synonymous variants: 152 observed, 155.09 expected, observed/expected ratio (o/e) 0.98, 90% interval 0.86 to 1.12.
Homologues: Orthologues: chimpanzee SLAMF6 (97% identical), macaque SLAMF6 (85% identical), pig SLAMF6 (54% identical), rat Slamf6 (43% identical), mouse Slamf6 (43% identical), zebrafish si:cabz01074946.1 (11% identical). Paralogues in human: CD84 (28% identical), LY9 (27% identical), SLAMF7 (27% identical), SLAMF9 (25% identical), SLAMF1 (19% identical), CD244 (16% identical), CD2 (16% identical), SLAMF8 (13% identical), CD48 (13% identical).
Diseases named in the same sentence as SLAMF6 in open-access papers:
SLAMF6 is named in the same sentence as 46 diseases in open-access papers, as found by Europe PMC text mining. Sharing a sentence is not in itself a finding about the gene and the disease. The quoted sentences say what the papers report.
melanoma (12 papers, 2019 to 2025). A malignant, usually aggressive tumor composed of atypical, neoplastic melanocytes. "The beneficial effect of SLAMF6 is mirrored by the clinical observation that high SLAMF6 expression in the tumor tissues of patients with breast cancer and melanoma is associated with superior progression-free survival and overall survival." (PMID 40558528, 2025). "We investigated the association between expression of SLAMF6 and immunological status in the tumor and survival in the cohort of breast cancer and melanoma." (PMID 38287061, 2024). "SLAMF6 has also been shown to have distinct clinical uses in X-linked lymphoproliferative diseases, systemic lupus erythematosus, and melanoma." (PMID 39354345, 2024). "Transcriptomic analysis of Tpe vs. Tex CD8 TIL subsets from B16 tumors and primary human melanoma tumors revealed that Tpes are enriched in Slamf6 and lack Entpd1 and Havcr2 expression, which encode Slamf6, CD39, and Tim3 cell surface proteins, respectively." (PMID 32174925, 2020). "In both mouse and human melanoma tumors we observed that Tcf7+ Pdcd1+ Tpe were enriched in Slamf6 and depleted of Havcr2 and Entpd1, which encode Slamf6, Tim3, and CD39 cell surface proteins, respectively." (PMID 32174925, 2020). "The results of this study showed that SLAMF6 expression was associated with elevated anti-cancer immune activity and better prognosis both in the ‘cold’ tumor (breast cancer) and the ‘hot’ tumor (melanoma)." (PMID 38287061, 2024). "In this line, the adoptive transfer of gp100-specific SLAMF6−/− T cells mediated durable melanoma regression, outperforming T cells of the same specificity with preserved SLAMF6 expression." (PMID 40558528, 2025). "IFN-γ secretion in response to CSPG4+ A375M melanoma cells was enhanced in CAR T cells with engineered SLAMF6 release compared to control CAR T cells, while IL-2 release was not affected." (PMID 40558528, 2025). "Ectopic overexpression of SLAMF6 in melanoma cells has been shown to reduce the activation of interacting T cells in vitro and to promote the expansion of melanoma cells in the presence of adoptively transferred T cells in vivo." (PMID 41044242, 2025). "Taken together, the enhanced functionality of CAR T cells with engineered soluble SLAMF6 was also corroborated for melanoma-targeting CAR T cells." (PMID 40558528, 2025). "Another study showed that inhibition of SLAMF6 with an anti-SLAMF6 antibody affected tumor growth of the B16 melanoma model." (PMID 38476238, 2024). "Collectively, these findings suggest that higher intra-tumoral SLAMF6 expression correlates with better prognosis in melanoma and breast cancer patients." (PMID 38287061, 2024). "According to the findings of a study, SLAMF6 is an inhibitory immune checkpoint whose absence allows potent CD8+ T cells to eliminate melanoma cells." (PMID 37251372, 2023). "To evaluate the role of SLAMF6 in melanoma-cognate T cells, we generated a new mouse strain by breeding Pmel-1 mice with SLAMF6 -/- mice." (PMID 32122464, 2020). "Adoptive transfer of Pmel-1 x SLAMF6 -/- T cells to melanoma-bearing mice resulted in lasting tumor regression in contrast to temporary responses achieved with Pmel-1 T cells." (PMID 32122464, 2020). "Compared to the wild-type cell line, the SLAMF6-expressing melanoma cells co-cultured with Pmel-1 CD8+ T cells led to decreased IFN-γ secretion by the lymphocytes." (PMID 32122464, 2020). "By transcriptomic and flow cytometry analyses of CD8 TILs from murine B16 and human primary melanoma, we found that Tpes can be efficiently captured by gating on Tim3- Slamf6+ CD39– cells." (PMID 32174925, 2020). "These experiments show that trans-activation of SLAMF6 on lymphocytes, which in this system was achieved with the SLAMF6-expressing melanoma, inhibits the melanoma-specific CD8+ T cell response and allows rapid tumor growth." (PMID 32122464, 2020).
melanoma (continued). "Depleting SLAMF6 improved CD8+ T cells in the short and long-term, as was most evident when the WT Pmel-1 cells induced the regression of melanoma only for a limited period while the Pmel-1 x SLAMF6 -/- cells led to lasting responses in mice." (PMID 32122464, 2020). "The beneficial effect of the soluble ectodomain of SLAMF6 prompted us to generate melanoma-specific SLAMF6 -/- T cells, to characterize the role of the receptor in a solid tumor model." (PMID 32122464, 2020). "Comparing IFN-γ secretion in response to melanoma cells by Pmel-1 versus Pmel-1 x SLAMF6 -/- lymphocytes showed that cytokine production by the Pmel-1 x SLAMF6 -/- lymphocytes was significantly higher at all effector-to-target ratios (p=0.05)." (PMID 32122464, 2020). "To test if this superior activation also affects anti-tumor immunity, we characterized Pmel-1 x SLAMF6 -/- melanoma specific T cells in the effector phase." (PMID 32122464, 2020). "In its absence, TCR triggering of anti-melanoma CD8+ T cells yielded a strong effector phenotype, higher IFN-γ secretion, improved cytolysis, and better outcomes in the adoptive transfer of SLAMF6 -/- anti melanoma CD8+ T cells to treat established melanoma." (PMID 32122464, 2020). "Accordingly, high SLAMF6 levels are a surrogate indicator for immune-favorable tumor microenvironments of breast cancer and melanoma; SLAMF6high tumors are significantly enriched with gene expression patterns associated with T cell activation and effector functions." (PMID 40558528, 2025). "Previous studies have shown that SLAMF6 expression is associated with improved progression-free and overall survival in breast cancer and melanoma, in which SLAMF6+ CD8+ T cells maintain the ability of multifunctionality and contribute to long-term tumor control." (PMID 40724541, 2025). "In this context, SLAMF6 (signaling lymphocytic activation molecule family-6) is raising particular interest since it was identified as a favorable target for augmenting the functionality of CD8+ T cells against melanoma cells, both in vitro and in vivo." (PMID 40558528, 2025). "Notably, systemic infusion of soluble SLAMF6 into melanoma-bearing mice enhanced the persistence and performance of melanoma-specific T cells." (PMID 40558528, 2025). "Using the publicly available data of The Cancer Genome Atlas (TCGA) and single-cell (sc) profiling of breast cancer (GSE161529), our data demonstrate that high expression of SLAMF6 in the tumor correlates with better patient survival and elevated immune activity in breast cancer and melanoma." (PMID 38287061, 2024). "However, among Pdcd1+ Tim3– Slamf6+ cells we found heterogeneous expression of Entpd1, a marker of Tex, both in murine and human melanoma tumors." (PMID 32174925, 2020). "As shown, the SLAMF6-expressing melanoma suppressed T cell efficacy and consequently grew faster." (PMID 32122464, 2020). "SLAMF6 expressed in trans by a melanoma target inhibits anti-tumor T cell reactivity." (PMID 32122464, 2020). "Importantly, Pmel-1 x SLAMF6 -/- T cells produced higher levels of granzyme B in response to melanoma compared to Pmel-1 T cells, which are already strong killers due to their TCR design." (PMID 32122464, 2020). "Our findings demonstrate that high SLAMF6 expression is associated with better prognosis, expression of TCF7 (encoding T-cell factor 1), and increased gene signatures associated with conventional type 1 dendritic cells and effector function of T cells in melanoma and breast cancer." (PMID 38287061, 2024). "CD28-ζ CAR T cells releasing soluble SLAMF6 increased IFN-γ secretion and augmented CD25 upregulation on CD4+ CAR T cells upon CAR engagement by pancreatic carcinoma and melanoma cells." (PMID 40558528, 2025). "In vitro, gp100-specific SLAMF6−/− T cells evinced a higher cytotoxic capacity and a higher secretion of IFN-γ in response to gp100-expressing melanoma cells." (PMID 40558528, 2025).
melanoma (continued). "Compared to conventional CAR T cells, SLAMF6-releasing CAR T cells displayed superior cytotoxicity and cytokine release against pancreatic adenocarcinoma and melanoma cells." (PMID 40558528, 2025). "Next, we investigated the relationship between SLAMF6 expression and immune activity in the TME of breast cancer and melanoma." (PMID 38287061, 2024). "In this study, we demonstrate the immunological relevance and prognostic significance of SLAMF6 expression in the TME of human breast cancer and melanoma." (PMID 38287061, 2024). "In summary, the results of this study demonstrate that high expression of SLAMF6 in TME correlates with elevated immune activities and better prognosis both in breast cancer and melanoma." (PMID 38287061, 2024). "This was consistent with the finding from our scRNA-seq analysis which identified SLAMF6+ cells expressing TCF7, effector- and memory-related genes, compatible to the subset of progenitor-exhausted T cells identified in the TME of melanoma patients." (PMID 38287061, 2024). "Furthermore, high expression of SLAMF6 is associated with the elevation of anti-cancer immune response represented by the enrichment of gene sets associated with proinflammatory, IFN-γ and T-cell response, and improved survival in patients with breast cancer and melanoma." (PMID 38287061, 2024). "To elucidate the net function of SLAMF6, we generated a transgenic mouse with the Pmel-1 melanoma-specific T-cell receptor (TCR) expressed in CD8+ T cells, in which the SLAMF6 gene was knocked out." (PMID 32122464, 2020). "In this report, we show for the first time that SLAMF6 -/- CD8+ T cells display improved anti-melanoma activity and prevent melanoma growth more effectively than CD8+ T cells with intact and functional SLAMF6." (PMID 32122464, 2020). "In summary, melanoma-specific T cells lacking SLAMF6 showed improved functional capacity both in vitro and in vivo and induced longer lasting tumor remission with longer tumor control compared to their wild-type counterparts." (PMID 32122464, 2020). "mAb directed against SLAMF6 considerably reduces the peritoneal cavity leukemic load and slows tumor development in B cell-related leukemias, lymphomas, and nonhematopoietic cancers such as melanoma." (PMID 37251372, 2023). "TCR triggering of anti-melanoma CD8+ T cells in SLAMF6 knockout mice resulted in a robust effector phenotype, increased IFN-γ production, enhanced cytolysis, and improved outcomes in the adoptive transfer of SLAMF6-/- anti-melanoma CD8+ T cells to treat existing melanoma." (PMID 37251372, 2023). "By breeding Pmel-1 mice with SLAMF6 -/- mice, we generated donors for T cells lacking SLAMF6 and expressing a transgenic TCR for gp100-melanoma antigen." (PMID 32122464, 2020). "In the past, we described that targeting SLAMF6 with its soluble ectodomain yielded CD8+ T cells that do not need IL-2 supplementation, either in vitro or in vivo, to eradicate established melanoma." (PMID 32122464, 2020).
lupus (9 papers, 2008 to 2024). "Polymorphisms within the region of Slamf6 (Ly108) have been implicated in systemic lupus erythematosus (SLE)." (PMID 18485879, 2008). "For example, polymorphisms in the Ly108 gene (corresponding to SLAMF6 in humans) result in the generation of a Ly108 splice variant in lupus-prone mice that is involved in the pathogenesis of SLE." (PMID 28387859, 2017). "In disease models of systemic lupus erythematosus, SLAMF6 promotes the differentiation of T cells into Th17 cells and promotes the recruitment of RORγT to the IL-17A promoter." (PMID 39354345, 2024). "Previous studies revealed that SLAMF6 functions as an inhibitory receptor that controls autoimmunity in systemic lupus erythematosus." (PMID 31672930, 2019). "SLAMF3 and SLAMF6 co-stimulation increases IL-17A production by Th17 cells and the correlation between their surface expression and disease activity in systemic lupus erythematosus has been reported." (PMID 29662641, 2018). "Previous studies of Slamf1-/- and Slamf6-/- mice that were backcrossed to C57Bl/6 mice have used lupus-prone (129 x B6) Sle1b mice as WT controls, due to residual 129-derived sequences around the SLAM loci, which were mutated in 129 ES cells." (PMID 27258160, 2016). "However, the proportion of SLAMF6-expressing CD4 T cells was higher in the active lupus patients compared with the patients in remission." (PMID 28387859, 2017).
leukemia (6 papers, 2019 to 2025). A malignant (clonal) hematologic disorder, involving hematopoietic stem cells and characterized by the presence of primitive or atypical myeloid or lymphoid cells in the bone marrow and the blood. "The proportions of CD4+, CD8+ and regulatory T cells were found to be unaffected by SLAMF6 expression on the leukemia cells." (PMID 41044242, 2025). "However, AML cases with high SLAMF6 expression on the leukemia cells were found to have higher frequencies of CCR7+CD45RA+ T cells, an immunophenotype associated with naive cells." (PMID 41044242, 2025). "The selective expression also makes SLAMF6 an attractive marker for separating LSCs from hematopoietic stem cells and could potentially be used to track the leukemia cell population over time." (PMID 41044242, 2025). "It has been shown that anti-SLAMF6 could correct CD8 dysfunction in leukemias and lymphomas." (PMID 38562928, 2024). "BETi synergized with anti-PD1 in vivo, resulting in the reduction of circulating leukemia cells, enrichment of CD8+ T cells in the bone marrow, and increase in expression of Tcf7, Slamf6, and Cxcr5 in CD8+ T cells." (PMID 36681742, 2023).
lymphoma (5 papers, 2017 to 2025). A malignant (clonal) proliferation of B- lymphocytes or T- lymphocytes which involves the lymph nodes, bone marrow and/or extranodal sites. "Furthermore, anti-SLAMF6/CD352 monoclonal antibodies demonstrated anti-tumor activity against CA46 human lymphoma xenografts in nude mice and against systemically disseminated Raji human lymphoma cells in severe combined immunodeficient mice." (PMID 38612827, 2024). "In pathological conditions, SLAMF6 is highly expressed in CLL and B lymphocytes of lymphoma patients." (PMID 29662641, 2018). "Microarray analyses revealed significant upregulation of a multitude of NK-activating and costimulatory ligands across varied b-NHL cell lines and primary lymphoma cells, including ULBP1, CD72, CD48, and SLAMF6." (PMID 29312292, 2017).
Autoimmunity (4 papers, 2014 to 2021). The occurrence of an immune reaction against the organism's own cells or tissues. "Previous studies have determined that anti-SLAMF6 antibodies can have a therapeutic effect in autoimmunity and cancer." (PMID 31199820, 2019). "Mixed reports of SLAMF6/Ly108 expression and function in autoimmunity exist." (PMID 33936082, 2021). "On the other hand, others have reported that deficient SLAMF6/Ly108 signaling reduces BCR signaling, lowers the frequency of B-T cell conjugates, resulting in loss of self-tolerance, culminating in autoantibody production and autoimmunity." (PMID 33936082, 2021). "Some of the mutated genes (SLAMF6, IRF1) have previously been associated with autoimmunity." (PMID 28635960, 2017).